PLK1 (polo like kinase 1)
Diseases named in the same sentence as PLK1 in open-access papers (continued):
Sharing a sentence is not in itself a finding about the gene and the disease.
lung adenocarcinoma (continued). "In the current study, PLK1 expression was elevated in lung adenocarcinoma and lung squamous cell carcinoma, which was consistent with the findings of a great deal of previous work." (PMID 34080290, 2021). "The difference of PLK1 between lung squamous cell cancer and lung adenocarcinoma would be most likely to be due to tumor heterogenicity." (PMID 28724602, 2017). "The status of PLK1 was observed in lung adenocarcinoma, lung squamous cell carcinoma, and normal lung tissues through analyzing microarray dataset (GEO accession numbers: GSE1213 and GSE 3627)." (PMID 28724602, 2017). "In our results, the levels of PLK1 in lung squamous cell carcinoma tissues were higher than that in lung adenocarcinoma tissues." (PMID 28724602, 2017). "In our initial study, we analyzed microarray datasets, and found PLK1 overexpressed in lung squamous cell carcinoma tissues compared with lung adenocarcinoma tissues." (PMID 28724602, 2017). "The implication of PLK1 in Docetaxel resistance was indeed recently shown in lung adenocarcinoma cells." (PMID 24525428, 2014). "PLK1 (Polo-like kinase 1) plays a critical role in the progression of lung adenocarcinoma (LUAD)." (PMID 38885192, 2024). "Moreover, DLGAP5 knockdown significantly inhibited cell proliferation and PLK1 expression in lung adenocarcinoma." (PMID 39624268, 2024). "The Polo-like kinase 1 (PLK1) pathway is crucial for cell cycle regulation and mitotic progression, and its overexpression has been associated with poor prognosis in various cancers, including lung adenocarcinoma (LUAD)." (PMID 39777332, 2024). "Additionally, multivariable Cox regression analysis demonstrated that PLK1 is an independent prognostic factor in lung adenocarcinoma (LA)." (PMID 37744268, 2023). "In lung adenocarcinoma, down-regulation of PLK1 expression obviously suppressed cell proliferation and induced cell cycle arrest and apoptosis in vitro, and the combination of PLK1-shRNA and low-dose gemcitabine produced an additive antitumor activity on the lung tumors in vivo." (PMID 28724602, 2017). "Interestingly, we further found the levels of PLK1 in lung squamous cell carcinoma tissues were higher than that in lung adenocarcinoma tissues." (PMID 28724602, 2017). "PLK1 also promotes the polarization of tumor-associated macrophages to upregulate the expression of IL-1A/1B, VEGFA, and IL-6, and the increased activity of these genes and factors is inversely associated with survival in patients with advanced lung adenocarcinoma." (PMID 40612941, 2025). "Furthermore, the regulation of the necroptosis pathway, which is closely associated with the inflammatory environment induced by IL-4/IL-13, may be involved in PLK1-mediated modulation of the immune microenvironment in lung adenocarcinoma (LA) patients." (PMID 37744268, 2023). "Immunohistochemical data from the HPA database, encompassing both lung adenocarcinoma (LUAD) and lung squamous cell carcinoma (LUSC), revealed significantly higher PLK1 expression in NSCLC patient tumor tissues compared to normal tissues." (PMID 41539998, 2026). "The dot plot displayed elevated levels of PLK1 observed in breast (BRCA), liver (LIHC), and lung adenocarcinoma (LUAD) as indicated by transcript per millions (TPM)." (PMID 41404416, 2025). "In lung adenocarcinoma, SKA3 was identified as an oncogene promoting cell growth and migration by PLK1-mediated SKA3 phosphorylation and stimulating metastasis through the activation of PI3K-AKT signaling." (PMID 38791174, 2024).
lung adenocarcinoma (continued). "We detected PLK1 expression by RT-qPCR in normal lung epithelial cells Base-2b, and lung adenocarcinoma cell lines A549 and NCI-H1299, and showed that PLK1 was greatly more highly expressed in lung adenocarcinoma cells than in normal cells (p < 0.001)." (PMID 37744268, 2023). "However, the role of PLK1 and necroptosis in lung adenocarcinoma (LA) remains unclear." (PMID 37744268, 2023). "Among them, CRABP2, KAT2A, BIRC5, ABCC3, PLK1, IGHG1, and EPCAM were upregulated in lung adenocarcinoma samples, while FABP4 was downregulated in lung adenocarcinoma samples." (PMID 35909589, 2022). "Taken together, TSA was verified to suppress the progression of lung adenocarcinoma by inducing cell apoptosis, arresting cell cycle through regulating CCNA2-CDK2 complex and AURKA/PLK1 pathway." (PMID 34880385, 2021). "Here, we show that vimentin phosphorylated by PLK1, triggers TGF-β-signaling, which consequently leads to metastasis and PD-L1 expression for immune suppression in lung adenocarcinoma." (PMID 33963314, 2021). "More direct evidence needs to be provided that TSA does indeed treat lung adenocarcinoma through the CCNA2-CDK2 complex and AURKA/PLK1 molecule." (PMID 34880385, 2021). "Targeting PLK1 with shRNA or non-functional mutants downregulated ABCB1, ABCC9, and ABCG2 in paclitaxel-resistant lung adenocarcinoma (LUADTXR), similar to the downregulation effects from treatment with PLK1 inhibitors." (PMID 34503223, 2021). "Research has shown that PLK1-induced phosphorylation of Vimentin promotes PD-L1 expression by activating TGF-β signaling and interacting with p-Smad2/3, contributing to metastatic progression in lung adenocarcinoma (LUAD)." (PMID 40612941, 2025). "However, despite the growing body of evidence highlighting the crucial part of Polo-like kinase 1 (PLK1) in tumorigenesis and tumor progression, studies on the role of PLK1 in lung adenocarcinoma (LA) are limited." (PMID 37744268, 2023). "In this research, samples of lung adenocarcinoma were interrogated with TME-related genes, among which high expression of PLK1, LDHA, FURIN, FSCN1, and RAB27B was correlated with poor OS, while high expression of MS4A1 was correlated with longer OS compared with the MS4A1 low expression." (PMID 37604869, 2023). "As shown in immunohistochemistry image from HPA platform, PLK1 protein showed a differentiation in neither lung adenocarcinoma nor lung squamous cell carcinoma." (PMID 34080290, 2021). "The clinical correlation between expression of both vimentin and PLK1, and overall survival rates of patients was significant in lung adenocarcinoma but not in squamous cell carcinoma." (PMID 33963314, 2021). "Thus, PLK1-mediated phosphorylation of vimentin activates TGF-β signaling pathway, leading to the metastasis and immune escape through the expression of PD-L1, functioning as a shuttling protein in lung adenocarcinoma." (PMID 33963314, 2021).
neuroblastoma (40 papers, 2012 to 2025). Neuroblastoma (NB) is the most common solid, extracranial childhood tumor. "In SEQC-498 cohorts containing 498 neuroblastoma patients' samples, high PLK1 expression (>median) was remarkable associated with both poor relapse free and overall survival of patients." (PMID 32231733, 2020). "Evidence suggests that certain oncogenic pathways and cell cycle regulators such as NF-kB, PI3K/mTOR, hedgehog and polo-like kinase 1 (PLK1) are overexpressed and activated in high risk neuroblastoma." (PMID 26934655, 2016). "Intriguingly, one of the primary functions of AURKA is the activation of PLK1 by direct phosphorylation of Thr210, and high expression of PLK1 is also significantly associated with high-risk neuroblastoma and unfavourable patient outcome." (PMID 22305495, 2012). "These preclinical findings indicate PLK1 inhibitors may be effective for patients with high-risk or relapsed neuroblastomas with upregulated PLK1 and might be considered for entry into early phase clinical trials in pediatric patients." (PMID 28036269, 2017). "PLK1 upregulation in primary neuroblastomas strongly correlates with high-risk disease." (PMID 28036269, 2017). "Therefore, to identify a most efficacious treatment for neuroblastoma, we investigated the efficacy of NF-kB/mTOR dual-inhibitor 13-197, hedgehog inhibitor vismodegib and PLK1 inhibitor BI2536 alone or combined with topotecan against high-risk neuroblastoma." (PMID 26934655, 2016). "In addition, overexpression and activation of the key cellular pathways such as NF-kB, mTOR, hedgehog and PLK1 molecules are associated with resistance to therapy in neuroblastoma." (PMID 26934655, 2016). "High polo-like kinase 1 (PLK1) expression has been linked to poor outcome in neuroblastoma (NB), indicating that it represents a relevant therapeutic target in this malignancy." (PMID 26046302, 2016). "siRNA PLK1-LNPs achieved significant PLK1 gene silencing by more than 2-fold and improved cell targeting by 1.2 to over 4.5 times in EGFR+ high-risk neuroblastoma cells." (PMID 40880603, 2025). "Based on our data, depletion of PDPK1 in CHP-134 cells does not impact steady-state protein levels of N-MYC as has been seen for shRNA-mediated knockdown or chemical inhibition of PLK1 in neuroblastoma cells." (PMID 38605297, 2024). "ChIP experiments performed on neuroblastoma and lymphoma cell lines also demonstrated a significant recruitment of c-Myc to the PLK1 E-box, suggesting that c-Myc directly regulates the PLK1 transcriptional program." (PMID 36902175, 2023). "BI-2536 is a small molecule inhibitor of PLK1 and significantly reduced cell viability by inducing cell cycle arrest and cell apoptosis in neuroblastoma and triple-negative breast cancer." (PMID 36476988, 2022). "A PLK1/FBXW7/N-MYC pathway has been demonstrated in neuroblastoma, where PLK1 phosphorylates FBXW7, promotes FBXW7 degradation and leads to the stabilization of N-MYC." (PMID 33494392, 2021). "Other strongly upregulated genes in this set were Dlk1, highly expressed in early sympathetic neuron progenitors and Plk1, a known therapeutic target in neuroblastoma." (PMID 34638267, 2021). "There is now a growing body of evidence showing that PLK1 has attractive therapeutic potential in treatment of various types of cancers, including neuroblastoma." (PMID 32231733, 2020). "Polo-like kinase 1 (PLK1), a serine/threonine kinase that promotes G2/M-phase transformation, has an elevated expression level in high-risk neuroblastoma and is associated with poor prognosis of patients." (PMID 33614505, 2020). "Polo-like kinase 1 (PLK1) is a serine/threonine-protein kinase expressed during mitosis and over expressed in multiple cancers, including neuroblastoma." (PMID 32231733, 2020). "In this study, we employed BI 2536--- the PLK1 inhibitor ---to assess the role of PLK1 in neuroblastoma and the anti-cancer efficacies of BI 2536 in neuroblastoma cells." (PMID 32231733, 2020).
neuroblastoma (continued). "Inhibition of PLK1 by BI 2536 effectively exerted anti-proliferation effect and triggered apoptosis in a panel of neuroblastoma cell lines." (PMID 32231733, 2020). "Another recent study showed that knockdown of LGALS1 can suppress autophagy 46, as well as we observed in neuroblastoma cell by PLK1 inhibition." (PMID 32231733, 2020). "Neuroblastoma CSCs have been previously reported to highly express the serine/threonine kinase, Polo-like kinase 1, a known inducer of G2/M-phase transition." (PMID 31191243, 2019). "PLK1 inhibitor blocks the growth and survival of neuroblastoma tumor initiating cells in a therapeutic xenograft model." (PMID 31191243, 2019). "Here we present preclinical data for the efficacy of the PLK1 inhibitor, GSK461364, against models for high-risk neuroblastoma." (PMID 28036269, 2017). "Neuroblastoma cell lines have previously been shown to express high PLK1 protein levels, similar to expression in primary tumors." (PMID 28036269, 2017). "Our experiments show that GSK461364-mediated PLK1 inhibition significantly reduced neuroblastoma cell viability and colony-forming ability in vitro, even when applied in short-term treatment pulses." (PMID 28036269, 2017). "Here we analyzed the effects of GSK461364, a competitive inhibitor for ATP binding to PLK1, on typical tumorigenic properties of preclinical in vitro and in vivo neuroblastoma models." (PMID 28036269, 2017). "Gorlick and colleagues treated a panel of predominantly MYCN-amplified neuroblastoma cell lines grown as xenograft tumors in CB17SC scid−/− mice with the PLK1 inhibitor, volasertib." (PMID 28036269, 2017). "We here show that inhibiting PLK1 with GSK461364 effectively reverted these effects, causing G2/M arrest accompanied by reduced proliferation and apoptosis in neuroblastoma cells." (PMID 28036269, 2017). "We and others have previously demonstrated that PLK1 is a potential therapeutic target in neuroblastoma, and that inhibition with the small molecule, BI2536, effectively decreased growth in cell and mouse models." (PMID 28036269, 2017). "Polo-like kinase 1 (PLK1) is a serine/threonine kinase that promotes G2/M-phase transition, is expressed in elevated levels in high-risk neuroblastomas and correlates with unfavorable patient outcome." (PMID 28036269, 2017). "Recently, we and others have presented PLK1 as a potential drug target for neuroblastoma, and reported that the BI2536 PLK1 inhibitor showed antitumoral actvity in preclinical neuroblastoma models." (PMID 28036269, 2017). "In summary, the combination of small molecule inhibitors of the NF-kB, hedgehog and PLK1 with topotecan demonstrated significant preclinical efficacy against neuroblastoma." (PMID 26934655, 2016). "Aberrant activation/expression of pathways/molecules including NF-kB, mTOR, hedgehog and polo-like-kinase-1 (PLK1) are correlated with poor-prognosis neuroblastoma." (PMID 26934655, 2016). "As inhibition of PLK1 using small molecule compounds has already been extensively studied in neuroblastoma, we decided to select CCND1 for further experiments." (PMID 26225123, 2015). "Real-time monitoring of cell growth showed that knockdown of CCND1 and PLK1 had the strongest effects in reducing the proliferation of neuroblastoma cells." (PMID 26225123, 2015). "In particular, silencing of CCND1 and PLK1 showed the most pronounced effects in reducing neuroblastoma cellular proliferation." (PMID 26225123, 2015). "It is noteworthy that neuroblastomas, pediatric tumours of the peripheral nervous system, also display greater sensitivity to Plk1 inhibitors." (PMID 24204733, 2013).
neuroblastoma (continued). "For example, by targeting PLK1, the small molecule inhibitor BI-2536 not only inhibited cancer cell proliferation, but also induced mitochondrial fusion, G2/M-phase blockade, and apoptosis in neuroblastoma cells." (PMID 40801655, 2025). "Notably, Myc facilitates the MYC–AURKA/PLK1 axis feed-forward circuit in lymphomas and neuroblastomas." (PMID 40813622, 2025). "This analysis provides evidence for the important role of PLK1 in neuroblastoma cell survival, and BI 2536 could be considered as a possible treatment strategy for neuroblastoma." (PMID 32231733, 2020). "Taken together, the current study showed that PLK1 was over expressed in neuroblastoma cells." (PMID 32231733, 2020). "The expression of SOCS2, which was found inhibited after PLK1 inhibition by RO3280 treatment in acute myeloid leukemia cells in our previous study 42, was also down regulated in neuroblastoma cells after PLK1 blockage, suggesting the involvement of SOCS2 in PLK1 pathway." (PMID 32231733, 2020). "Furthermore, by virtue of public neuroblastoma datasets, we showed that high expression of PLK1 was closely related to the prognosis outcome of neuroblastoma patients." (PMID 32231733, 2020). "But until now the role of PLK1 in neuroblastoma has not been fully understood." (PMID 32231733, 2020). "These evidences suggest that LGALS1 might serve downstream of PLK1 and contribute to the apoptosis induction and autophagy inhibition triggered by BI 2536 in neuroblastoma cells." (PMID 32231733, 2020). "In neuroblastoma cells, PLK1 enhances stability of MYCN by antagonizing FBW7-mediated degradation." (PMID 31455158, 2019). "Interestingly, the expression of 3 of these genes i.e. MELK, MYBL2 and PLK1 is remarkably highly correlated with FOXM1 expression levels in 200 neuroblastoma tumors (correlation coefficients >0.9) suggesting a very tight co-regulated transcriptional control." (PMID 30504901, 2018). "Interestingly, miR-34a, which acts as a tumor suppressor in neuroblastoma, has also been shown to downregulate E2F factors and is suggested to directly suppress PLK1 translation." (PMID 28036269, 2017). "A small molecule screen to identify kinase inhibitors that suppress neuroblastoma tumor initiating cell (TIC) proliferation identified PLK1 as a promising target whereas only exceedingly high inhibitor concentrations were cytotoxic for neural stem cells in this screen." (PMID 28036269, 2017). "Because PLK1 has been preclinically validated as a cancer therapeutic target, small-molecule inhibitors of PLK1 have become attractive candidates for treating cancers such as rhabdomyosarcoma and neuroblastoma." (PMID 29228610, 2017). "Aggressive neuroblastoma subtypes overexpressed both PLK1 transcripts and protein." (PMID 28036269, 2017). "We previously reported that PLK1 inhibitors and microtubule-interfering agents synergize to trigger apoptosis following prolonged mitotic arrest in ES, rhabdomyosarcoma (RMS) and neuroblastoma (NB) cells, i.e. tumor entities that have been reported to overexpress PLK1." (PMID 28881742, 2017). "BI2536 treatment resulted in complete shut-down of PLK1 expression in neuroblastoma cells." (PMID 26934655, 2016). "We next wanted to see whether combining these inhibitors of the NF-κB/mTOR, hedgehog and PLK1 with topotecan resulted in a corresponding declines in expression/activation of the respective pathways/molecules in neuroblastoma cells." (PMID 26934655, 2016). "Moreover, targeting PLK1 with small molecule compounds induced apoptosis and growth arrest in neuroblastoma tumor-initiating cells and reduced the growth of neuroblastoma xenografts in nude mice." (PMID 26225123, 2015). "Inhibition of PLK1 protein has an anti-proliferative effect on neuroblastoma cell proliferation." (PMID 22305495, 2012). "Thus, there is a clear role for PLK1 in tumor-initiating cells, a finding hinted at in recent data from neuroblastoma." (PMID 22390279, 2012).